FUBP1 (far upstream element binding protein 1)
Description:
Regulates MYC expression by binding to a single-stranded far-upstream element (FUSE) upstream of the MYC promoter. May act both as activator and repressor of transcription.
Synonyms: FBP; hDH V; FUBP
Tractability: PROTAC: UniProt records ubiquitination sites on it; ubiquitination databases record sites on it; its protein half-life has been measured; a small molecule that binds it is known.
Target class: Transcription factor
Gene: Protein-coding gene on chromosome 1 (77,944,055 to 77,979,527, reverse strand). Ensembl gene ENSG00000162613.
Subcellular location: Nucleus
Subcellular location (Human Protein Atlas): Nucleoplasm
Gene Ontology:
Molecular function: protein binding; RNA binding; mRNA 3'-UTR binding; single-stranded DNA binding; nucleic acid binding
Biological process: positive regulation of gene expression; regulation of gene expression; regulation of transcription by RNA polymerase II
Cellular component: nucleoplasm; nucleus
Genetic constraint (gnomAD): Loss-of-function variants: 3 observed, 28.02 expected, observed/expected ratio (o/e) 0.11, 90% interval 0.048 to 0.28. The upper end of that interval is the gene's LOEUF score, 0.28, which puts it in group 1 of 6, group 1 being the genes least tolerant of losing a copy. Missense variants: 261 observed, 362.3 expected, observed/expected ratio (o/e) 0.72, 90% interval 0.65 to 0.8. Synonymous variants: 135 observed, 124.17 expected, observed/expected ratio (o/e) 1.09, 90% interval 0.94 to 1.25.
Cancer hallmarks: invasion and metastasis (promotes); escaping programmed cell death (promotes); proliferative signalling (promotes)
Homologues: Orthologues: macaque FUBP1 (99% identical), pig FUBP1 (99% identical), guinea pig FUBP1 (99% identical), rat Fubp1 (98% identical), mouse Fubp1 (98% identical), zebrafish fubp1 (73% identical), Caenorhabditis elegans fubl-3 (27% identical), Caenorhabditis elegans fubl-4 (25% identical), Drosophila melanogaster mub (17% identical), Drosophila melanogaster ps (15% identical), Drosophila melanogaster Imp (13% identical), Caenorhabditis elegans nova-1 (12% identical), and 2 more. Paralogues in human: KHSRP (66% identical), FUBP3 (52% identical), NOVA1 (18% identical), IGF2BP2 (17% identical), NOVA2 (17% identical), PCBP4 (17% identical), PCBP3 (16% identical), IGF2BP3 (16% identical), IGF2BP1 (16% identical), PCBP2 (16% identical), HNRNPK (15% identical), PCBP1 (15% identical).
Diseases named in the same sentence as FUBP1 in open-access papers:
FUBP1 is named in the same sentence as 108 diseases in open-access papers, as found by Europe PMC text mining. Sharing a sentence is not in itself a finding about the gene and the disease. The quoted sentences say what the papers report.
oligodendroglioma (55 papers, 2012 to 2026). A well-differentiated (WHO grade II), diffusely infiltrating neuroglial tumor, typically located in the cerebral hemispheres. "1p/19q co-deletion was detected by fluorescence in situ hybridization (FISH) and Tempus xT 648 gene panel reported genomic variants in IDH1, TERT, CIC, and FUBP1, as expected for an oligodendroglioma." (PMID 39857783, 2025). "FUBP1 deletion is associated with oligodendroglioma and breast cancer, while FUBP1 also promotes the mobility of lung cancer." (PMID 39146021, 2024). "Mutations in the remaining allele of FUBP1 are frequently encountered in oligodendrogliomas carrying the 1p/19q co-deletion." (PMID 37372972, 2023). "Further, these alterations in oligodendroglioma along with loss of FUBP1 expression have been shown to be potential markers of rapid recurrence." (PMID 37291277, 2023). "The “double-agent” functions of the FUBP1 gene have been identified in a variety of cancers; for example, genomic loss-of-function mutations are linked with poor survival in oligodendrogliomas, suggesting a tumor-suppressive function of FUBP1." (PMID 33987449, 2021). "Previous reports showed that inactivating mutations of FUBP1 were detected in 15–20% of oligodendrogliomas, suggesting a tumor suppressive role of Fubp1." (PMID 32481602, 2020). "CIC and FUBP1 mutations are frequently mutated in IDH mutated 1p/19q-codeleted oligodendroglioma and the prognostic impact has been investigated in several series." (PMID 29663171, 2018). "Both findings corroborate observations of CIC and FUBP1 mutation heterogeneity across nine distinct samples from the same oligodendroglioma, including finding five distinct CIC mutants across nine tumor samples." (PMID 29616301, 2018). "In oligodendrogliomas FUBP1 expression was abolished because of mutations and it was considered a tumor suppressor." (PMID 28076379, 2017). "Co-deletion of 1p/19q was recently shown to be associated with CIC and FUBP1 mutations, mainly seen in oligodendroglioma and mutually exclusive with ATRX mutation." (PMID 24810474, 2014). "We have successfully established and serially passaged a grade III oligodendroglioma xenograft with the hallmark chromosome 1p and 19q losses and mutations including FUBP1, CIC, and IDH1 (R132H)." (PMID 23527265, 2013). "Twenty-one mutations including this one have been reported in 103 oligodendrogliomas with fourteen of the FUBP1 mutations in anaplastic cases." (PMID 23527265, 2013). "CIC and FUBP1 mutations occurred frequently in oligodendrogliomas (46% and 24%, respectively) but rarely in astrocytomas or oligoastrocytomas (<10%)." (PMID 22869205, 2012). "Among grade II-III gliomas, CIC and FUBP1 mutational status has only been investigated in oligodendrogliomas, oligoastrocytomas and preselected astrocytomas with 19q loss." (PMID 22869205, 2012). "FUBP1 mutation could be observed in approximately 15~30% of tumors with 1p/19q co-deletion; however, its specific functional role in oligodendroglioma pathogenesis remains unclear." (PMID 40426960, 2025). "Nevertheless, this conjecture may lose credibility if CIC and/or FUBP1 mutations are ubiquitous in oligodendrogliomas." (PMID 37185778, 2023).
oligodendroglioma (continued). "Inactivating FUBP1 mutations also occur in 15% to 30% of oligodendrogliomas." (PMID 36765553, 2023). "A recent study of the somatic mutational landscape of splicing factor genes across 33 cancer types revealed a significant association of loss-of-function (LoF) mutations affecting the remaining allele of FUBP1 with alternative splicing and gene downregulation in oligodendrogliomas." (PMID 37372972, 2023). "Moreover, mutations of homolog of Drosophila capicua transcriptional repressor (CIC) and far upstream element binding protein 1 (FUBP1) occur frequently in tumors with 1p/19q loss in oligodendrogliomas." (PMID 32825279, 2020). "Interestingly, inactivating mutations of FUBP1 were identified in a substantial fraction of oligodendrogliomas, suggesting the tumor-suppressive role of Fubp1." (PMID 32481602, 2020). "Second, 1p/19q codeletion might drive the development of oligodendroglioma through mechanisms other than loss of FUBP1 and CIC." (PMID 31217899, 2019). "FUBP1 mutations have also been identified in oligodendrogliomas." (PMID 29245897, 2017). "Based on the relatively low incidence of FUBP1 mutations, their concurrence with CIC mutations, and their occurrence in recurrent tumors, we hypothesize that FUBP1 mutations might constitute a later event in oligodendroglioma tumorigenesis." (PMID 24086756, 2013). "However, not all tumors with the 1p/19q co-deletion carried an alteration in the second allele of CIC (or FUBP1), indicating that other mechanisms or genes are involved in oligodendroglioma development." (PMID 24086756, 2013). "Mutations of FUBP1 were recently reported in a subset of oligodendrogliomas." (PMID 24086756, 2013). "Recurrent molecular genetic alterations, such as IDH1/2, FUBP1, CIC, and TERT promoter mutations, have been identified to co-occur with 1p/19q co-deletion in oligodendrogliomas." (PMID 40426960, 2025). "FUBP1 deletion has been frequently found in oligodendroglioma and identified as a “long tail” driver, in tandem with PTEN deletion, for breast cancer." (PMID 39146021, 2024). "This study also confirmed previous reports by our team and others identifying CIC and FUBP1 as potential oligodendroglioma tumor suppressor genes lost on chromosomes 1p and 19q, respectively." (PMID 35957904, 2022). "Oligodendrogliomas were characterized by a common 1p/19q deletion and mutations in CIC, FUBP1, Notch1, and TERT promoters." (PMID 35572524, 2022). "A hotspot TERT promoter mutation was detected in 11/13 samples, 5/13 samples had a FUBP1 mutation, 4/13 samples a CIC mutation similar to conventional oligodendrogliomas." (PMID 34967922, 2022). "Nevertheless, further studies are needed to elucidate the role of CIC/FUBP1 alterations in the pathogenesis of AO and oligodendrogliomas, in general." (PMID 34675774, 2021). "All of the oligodendroglioma tumor samples shared driver-like mutations in IDH1, TERTp, CIC, and FUBP1." (PMID 32904945, 2020). "It was also enriched for oligodendrogliomas (85%), mutations in NOTCH1, FUBP1, and CIC, and oligodendrocyte progenitor-specific expression." (PMID 32600353, 2020). "LGGs with an IDH1 mutation and 1p19q co-deletion show oligodendroglioma histological characteristics and arise from TERT activation, mutations in CIC and FUBP1, and activating alterations in the phosphoinositide-3-kinase (PI3K) pathway." (PMID 32120790, 2020).
oligodendroglioma (continued). "Of the genes already associated with the development of oligodendroglioma (IDH1/IDH2, CIC, and FUBP1), remarkably only the mutation in IDH1 (NM_005896:c.395G>A) was present in the primary O2005." (PMID 31217899, 2019). "FUBP1 and CIC were both mutated in only 12% (2/17) of oligodendrogliomas examined, and all had sustained a variant in IDH1." (PMID 31217899, 2019). "Most IDH-mt tumors with codeletion were histological oligodendrogliomas and harbored CIC, FUBP1, NOTCH1, and TERT promoter (TERTp) mutations." (PMID 31788444, 2019). "As previously identified, mutations in FUBP1 and IDH1 are closely associated with oligodendrogliomas, and are important prognostic and molecular markers for differentiating glioma phenotypes." (PMID 26246470, 2015). "Frequently occurring driver mutations in oligodendrogliomas include mutations in IDH1, CIC, FUBP1, TERT promoter and NOTCH." (PMID 25694352, 2015). "Recently, CIC and FUBP1 have been identified as candidate tumor suppressor genes in oligodendrogliomas with the typical 1p/19q co-deletion." (PMID 24086756, 2013). "We analyzed a cohort of 17 oligodendroglial tumor samples, consisting of nine cases diagnosed as oligodendroglioma (O) and eight as oligoastrocytoma (OA) for copy number variations (CNV); CIC, FUBP1 and IDH1/IDH2 mutations; and gene expression changes." (PMID 24086756, 2013). "The percentage of oligodendrogliomas with CIC mutations is in the range of 50 to 80%, whereas FUBP1 mutations have been found to occur in approximately 15% to 20% of oligodendrogliomas in three studies." (PMID 23527265, 2013). "The highest frequency of CIC and FUBP1 mutations occurred in grade II (38% and 14%, n=21) and grade III oligodendrogliomas (52% and 31%, n=29)." (PMID 22869205, 2012). "Recent exomic sequencing of oligodendrogliomas revealed inactivating mutations in two tumor suppressor genes: homolog of Drosophila capicua (CIC) and far-upstream binding protein 1 (FUBP1) in 53% and 15% of oligodendrogliomas, respectively." (PMID 22869205, 2012). "Some tumors with 1p/19q co‐deletion are accompanied by mutations in CIC and FUBP1, but these mutations do not seem essential for the establishment of the histological and clinical features of oligodendroglioma." (PMID 37533228, 2023). "Oligodendrogliomas with both CIC and FUBP1 mutations are exceedingly rare." (PMID 36765553, 2023). "Therefore, a more biologically informative and clinically relevant oligodendroglioma model would be introducing the 1p/19q co-deletion and other coordinating mutations (eg, TERT promoter, and FUBP1 or CIC) in IDH mutant cells of the oligodendrocytic lineage." (PMID 36225650, 2022). "Recurrent mutations in the capicua transcriptional repressor gene (CIC), on 19q and to a much lesser extent in the far upstream element (FUSE) binding protein 1 gene (FUBP1) on 1p31.1 have only recently been identified in oligodendrogliomas by using DNA next generation sequencing." (PMID 24086756, 2013). "In fact, while mutation of CIC is a more common denominator amongst oligodendrogliomas, mutation of FUBP1 is not." (PMID 23527265, 2013). "As for the clinical relevance of these molecular markers, inactivating mutations affecting FUBP1 have correlated with a shorter time to recurrence and CIC mutations have been associated with worse prognosis, especially in those patients with 1p/19q co-deleted oligodendrogliomas." (PMID 34675774, 2021).
oligodendroglioma (continued). "In addition, FUBP1 has been shown to be associated with poor prognosis in glioma patients, and mutations in CIC and FUBP1 have been reported to contribute to human oligodendroglioma." (PMID 29371945, 2017). "Oligodendroglioma (Omut-IDH,codel-1p/19q,G3), in which TERT (3/4 Patients), CIC (3/4 Patients), FUBP1 (1/4 Patients), and NOTCH1 promoter (1/4 Patients), which corroborates the frequency of mutations in these genes in patients with high-grade gliomas." (PMID 39767683, 2024). "CIC and FUBP1, transcription factors that counteract the RTK/Ras/ERK signaling pathway, have been reported in oligodendroglioma." (PMID 36998447, 2023). "The gene set includes IDH1, IDH2, BRAF, CDKN2A/B, PTEN, and NOTCH1, but misses CIC, FUBP1, ATRX, and H3-3A important for oligodendroglioma and astrocytoma diagnosis." (PMID 37908227, 2023). "In the 23 oligodendroglioma cases, CIC (70%), PIK3CA (35%), PIK3R1 (26%), and FUBP1 (22%) were detected." (PMID 35626060, 2022). "Further molecular studies identified mutations in TERT (telomerase reverse transcriptase), FUBP1 (far upstream element-binding protein 1), and CIC (capicua transcriptional repressor) in oligodendrogliomas." (PMID 32444979, 2020). "A paired analysis of primary and recurrent 1p/19q-codeleted oligodendrogliomas described distinct alterations in CIC and FUBP1 in the primary and the recurrent tumor." (PMID 29616301, 2018). "We analyzed 17 oligodendrogliomas and oligoastrocytomas by applying a comprehensive approach consisting of RNA expression analysis, DNA sequencing of CIC, FUBP1, IDH1/2, and array CGH." (PMID 24086756, 2013). "Among IDH1/2-mutant gliomas, TERTp (38.8%), CIC (24.3%), and FUBP1 (15.3%) alterations exhibited a subtype-specific distribution, with CIC/FUBP1 mutations predominant in oligodendrogliomas (62.0%/39.2%) and rare (<2%) in non-oligodendroglial subtypes." (PMID 41377022, 2025). "Our patient’s tumor harbored mutations in TERT, FUBP1, and CIC, which are common alterations in oligodendroglioma, but not clinically relevant." (PMID 39857783, 2025). "The alterations in FGFR4, KIT, and PEG3 were correlated with a short OS in astrocytoma, alterations in CDK4, FUBP1, and NTRK2 were correlated with a short OS in oligodendroglioma, and alterations in CDK4, CIC, FGFR3, and KMT5B were correlated with a short OS in glioblastoma." (PMID 36998447, 2023). "In addition, situations such as Sample 18 and 19, which appeared to be oligodendrogliomas, may demonstrate how FUBP1 and CIC mutations and histopathological features without the hTERT promoter mutation could potentially predict the presence of 1p19q codeletion." (PMID 32118206, 2020). "In IDH mutated 1p/19q-codeleted oligodendroglioma, both CIC and FUBP1 mutations were frequent events, but neither was associated with prognosis." (PMID 29663171, 2018). "The 1p deletion did not include FUBP1 but the region of loss on 19q did include CIC, both oligodendroglioma-implicated genes." (PMID 27028405, 2016).